CYP1A1 (cytochrome P450 family 1 subfamily A member 1)
Diseases named in the same sentence as CYP1A1 in open-access papers (continued):
Sharing a sentence is not in itself a finding about the gene and the disease.
breast carcinoma (continued). "ORs for CYP1A1 genotypes and breast cancer were close to the null in African Americans and whites." (PMID 15642161, 2005). "With regard to CYP1A1 M2-containing genotypes, Moysich and colleagues reported an OR for breast cancer of 2.9 (95% CI 1.2–7.5) in postmenopausal women with total PCBs between 3.72 and 19.04 ng/g and CYP1A1 M2-containing genotypes compared with women with low PCBs and non-M2-containing genotypes." (PMID 15642161, 2005). "In addition, THC could affect the CYP450 enzyme metabolic pathway and inhibit the expression of CYP1A1 and activation of the NF-κB pathway, thereby inhibiting the migration and invasion of breast cancer cells." (PMID 36707875, 2023). "However, CYP1A1 is constitutively expressed during breast cancer, contributing to its progression." (PMID 35678668, 2022). "Moreover, there is no clear association between the CYP1A1 gene polymorphism and breast cancer risk in various parts of the world." (PMID 29707532, 2018). "Therefore, we first examined whether Flavipin induces gene expression of Cyp1a1 in breast cancer cells." (PMID 27907195, 2016). "The studies conducted by Lee and Safe confirmed the inhibition of 2,3,7,8-tetrachlorodibenzo-p-dioxin (TCDD) induced CYP1A1 activity and expression by resveratrol at a dose of 10 μM in MCF7 and T47D breast cancer cell lines." (PMID 40807256, 2025). "According to a recent study, when MCF-7 breast cancer cells were treated with HSP (1–20 μM), aryl hydrocarbon receptor (Ahr) was inhibited, and the expression of CYP1A1, 1A2, and 1B1 was downregulated." (PMID 40427522, 2025). "On the other hand, in some systems, such as T47-D breast cancer cells, both I3C and DIM reduced CYP1A1 activity and expression induced by co-treatment with TCDD." (PMID 40807256, 2025). "In the human breast cancer cell line, MCF7 TMS effectively inhibited CYP1A1 expression and ethoxyresorufin-O-demethylase, a marker of CYP1A1 activity." (PMID 39339278, 2024). "Based on the experimental results, after CYP1A1 gene knockdown in breast cancer cells and administration with 80 μM of THC, breast cancer cells experienced significant apoptosis." (PMID 36707875, 2023). "The knockdown of CYP1A1 significantly enhanced the inhibitory effect of THC on the proliferation, metastasis, and apoptosis induction of breast cancer cells." (PMID 36707875, 2023). "After the overexpression of the CYP1A1 gene, experimental results showed that the inhibitory effect of high-dose THC on metastasis of breast cancer cells was significantly weakened." (PMID 36707875, 2023). "Significant levels of CYP1A1 mRNA and protein were detected in the ovarian cancer cell lines A2780 and SKOV-3 relative to their high expression in breast cancer cell lines." (PMID 38001897, 2023). "The transfected breast cancer cells were stimulated with THC (80 μM) for 48 h, and WB assay showed that NF-κB and p-IκBα expression increased in the CYP1A1 group compared with the THC group." (PMID 36707875, 2023). "A recent study suggests that aryl hydrocarbon receptor (Ahr) is blocked, and CYP1A1, 1A2, 1B1 expression is down-regulated when treated with HSP (1–20 μM) in MCF-7 breast cancer cells." (PMID 35128104, 2022). "Their activity as inducers of CYP1A1 and CYP1B1 in MDA-MB-468 and BT474 breast cancer cells was structure, response and cell type-specific." (PMID 36428667, 2022). "Consistently, a study confirmed that enzymes including CYP1A1, CYP2C19, ABCB1, and other key transporters involved in drug resistance were significantly upregulated in the anthracycline-R breast cancer cell lines." (PMID 36551262, 2022). "Conversely, in MCF-7 breast cancer cells exposed to TCDD, ligand-bound AhR recruits ERα to the XREs located upstream of the CYP1A1 and CYP1B1 genes." (PMID 33451129, 2021). "In MCF-7 breast cancer cells treated with DMBA, one of the PAHs, enzyme kinetic analysis revealed that BAI is a competitive inhibitor of CYP1A1 activity." (PMID 32526964, 2020).
breast carcinoma (continued). "Alyssin and ITC-2 decrease the activity of enzymes CYP1A1 and CYP1A2 induced by benzo[a]pyrene in MCF-7 breast cancer cells." (PMID 32471217, 2020). "Both flavonoids suppressed pro-intravasative trigger factors in MDA-MB231 breast cancer cells, specifically MMP1 expression and CYP1A1 activity." (PMID 29593542, 2018). "The mechanism of interaction between AhR and CYP1A1 or CYP2, where both are involved in the metabolism of estrogen which may lead to alteration in steroid levels modulating bioactivation of therapeutic agents and xenobiotics and elevating the risk of breast cancer in smoking women." (PMID 29707532, 2018). "Another mechanism of breast cancer emboli to cross the endothelial barrier is the secretion of 12(S)-HETE which, in MDA-MB231 cells, is produced by CYP1A1." (PMID 29593542, 2018). "To address this point, we examined the effects of two well-known AhR agonists and potent CYP1A1 inducers, TCDD and DMBA, on mammosphere formation numbers as an indicator of increased or decreased in the self-renewal capacity of breast cancer cells." (PMID 28103884, 2017). "According to these results, human breast cancer MCF-7 cell line, that showed the highest expression levels, was utilized as a study model for investigating the role of AhR/CYP1A1 pathway in regulating and controlling CSCs." (PMID 28103884, 2017). "We previously demonstrated that constitutively active AHR in breast cancer lines preferentially drives Cyp1b1 expression while an exogenous ligand, e.g. DMBA, tends to induce greater fold-increases in Cyp1a1 than Cyp1b1." (PMID 26984638, 2016). "Our results confirm the hypothesis that CYP1A1Ile462Val, in association with a long period of active smoking, could be a possible breast cancer risk factor and also support the main effect of CYP1A1 in estrogenic metabolism rather than in tobacco carcinogen activation in breast cancer patients." (PMID 27754415, 2016). "CYP1A1, AHR, AR, CYP1A, CYP1B1 and PTGS2 genes are common in both PCB-gene and PCB-gene-breast cancer groups." (PMID 26512648, 2015). "More importantly CYP1A1 was reported by Rodriguez and Potter to regulate breast cancer cell proliferation and survival via suppression of AMPK signalling, whereas with respect to cancer metastasis CYP1A1 has been shown to be involved in β-catenin signaling." (PMID 24358191, 2013). "The highest level of CYP1A1 mRNA was found in both breast cancer cell lines: MCF-7 (RA = 2.04 ± 0.43) and MDA-MB-231(RA = 1.86 ± 0.30) used in our screening; similarly the highest level of CYP1A1 protein was found in these lines." (PMID 23873331, 2013). "The presence of AHR, ARNT and ERα at the dioxin-inducible CYP1A1 enhancer and the E2-inducible pS2 promoter has already been documented in MCF7 cells and other breast cancer cell lines." (PMID 22235307, 2012). "The effect of the dietary flavonoid galangin on the metabolism of 7,12-dimethylbenz[a]anthracene (DMBA), the activity of cytochrome P 450 1A1 (CYP1A1), and the expression of CYP1A1 in MCF-7 human breast carcinoma cells was investigated." (PMID 10188874, 1999). "Finally, T47D cells are a cancer cell line notably expressing AHR that activates CYP1A1 and CYP1B1 expression and many downstream genes frequently found in breast cancers." (PMID 41336283, 2025). "Similarly, increased expression of CYP1A1 and CYP1B1 in MCF7 breast cancer cells as a result of treatment with methoxylated flavones, eupatorine, and cirsiliol was observed." (PMID 40807256, 2025). "Metformin may act as an inhibitor of AhR and its downstream genes, as it reduces expression of CYP1A1 and CYP1B1 in MCF-7 breast cancer cells by suppressing the AhR signaling pathway." (PMID 41440753, 2025). "However, in some systems, for e.g., human T47-D breast cancer cells, both I3C and DIM reduced CYP1A1 activity." (PMID 39339278, 2024).
breast carcinoma (continued). "Furthermore, after overexpression of CYP1A1, the inhibitory effects of THC on the proliferation, metastasis, and induction of apoptosis in breast cancer cells were weakened." (PMID 36707875, 2023). "Meanwhile, the experimental results showed that the survival rate of breast cancer cells increased after the overexpression of CYP1A1 compared with the blank control group, and the inhibitory effect of THC on the proliferation of breast cancer cell was weakened after the overexpression of CYP1A1." (PMID 36707875, 2023). "Meanwhile, after the overexpression of the CYP1A1 gene in breast cancer cells, the experimental results show that the cells in the THC group undergo apoptosis, whereas the breast cancer cells in the CYP1A1 group are in a good state with almost no apoptosis." (PMID 36707875, 2023). "Furthermore, the metabolism of quercetin by the CYP1 enzyme, particularly CYP1A1 and CYP1B1, intensifies their antiproliferative effects in breast cancer cells." (PMID 36118099, 2022). "(iv) Synthetic AhR ligands including pharmaceuticals: Initial studies in this laboratory identified MCDF as a partial AhR antagonist which inhibited induction of CYP1A1 by TCDD in cell culture, whereas MCDF exhibited AhR-dependent antiestrogenic activity in the mouse uterus and breast cancer cells." (PMID 36428667, 2022). "Notably, among the most upregulated genes we find the well-known stemness marker CXCR4, CYP1A1, which was reported to control bCSCs proliferation, development and self-renewal, and TM4SF1 that was shown to promote breast cancer stem cell traits." (PMID 34680485, 2021). "Molecular modeling showed CYP1B1 favored a ring orientation to the heme group compared to CYP1A1; therefore, activation of CYP1B1 and conversion of luteolin to the hydroxylated form may enhance antiproliferative activity against breast cancer." (PMID 34594472, 2021). "In MCF-7 human breast cancer cells, chrysoeriol did not affect the CYP1A1 and CYP1B1 gene expression, but significantly inhibited the production of 4-MeOE2 without any effects on the formation of 2-MeOE2." (PMID 34462889, 2021). "This trend was in line with previous reports documenting that constitutively active AHR in rodent and human mammary tumors associated with elevated CYP1B1, but not CYP1A1 or mRNA." (PMID 31652854, 2019). "To test our hypothesis, we initially investigated the constitutive expression of AhR and its regulated genes, CYP1A1 and CYP1B1 in different breast cancer cell lines." (PMID 28103884, 2017). "In addition to increasing CYP1A1/1A2/1B1 expression, AF induces nuclear translocation of AhR and stimulates protein-DNA complexes formed on DREs in AF-sensitive MCF7 human breast cancer cells, suggesting that AF is an AhR agonist." (PMID 24885022, 2014). "Furthermore, others demonstrated that stable knockdown of ERα expression by short-hairpin RNA in T47D human breast cancer cells and HC11 mouse mammary cells significantly reduced TCDD-induced CYP1A1 expression." (PMID 24058584, 2013). "Consistent with other investigators' observations in breast cancer cells, we observed the recruitment of AHR and ARNT on the human CYP1A1 enhancer in a TCDD-dependent fashion and ERα was greatly enriched only after treatment with a combination of 2 nM TCDD and 10 nM E2." (PMID 22235307, 2012). "CYP1A1 up-regulation by Triflorcas was independent of its action on Met as found also in cells, such as in the human breast cancer BT474 cells, which are addicted to ErbB1 signaling." (PMID 23071625, 2012). "Some authors have reported that the estrogen receptor-negative breast cancer cell line MDA-MB-468 expresses CYP1A1 active protein only after treatment with the CYP1 inducer TCDD." (PMID 18454852, 2008). "No study has examined the associations of polymorphisms in CYP1A1, CYP1B1, and COMT with breast cancer risk among women with BBD." (PMID 16808847, 2006).
breast carcinoma (continued). "Thus, metformin decreases CYP1A1 and CYP1B1 expression in breast cancer cells by suppressing the AhR signaling pathway and may act as a potential chemopreventive agent against CYP1B1- and CYP1A1-mediated carcinogenesis and cancer progression." (PMID 41440753, 2025). "The predictions revealed that the mechanism of sinapic acid in breast cancer may be due to regulation of multiple proteins like CTNNB1, PRKCA, CASP8, SIRT1, and cytochrome enzymes (CYP1A1 & CYP3A4); the majorly regulated pathway was predicted to be ‘Pathways in cancer’." (PMID 38081857, 2023). "The predictions revealed that the mechanism of sinapic acid in breast cancer may be due to multiple pathways and proteins like β-catenin, PRKCA, CASP8, and cytochrome enzymes (CYP1A1 and CYP3A4); the majorly regulated pathway was predicted to be “Pathways in cancer”." (PMID 38081857, 2023). "Furthermore, inhibition of CYP1A1 in the luminal MCF‐7 and triple negative MDAMB‐231 breast cancer cell lines decreased proliferation and clonogenic survival, all of which suggests an association of CYP proteins with cellular proliferation, although further studies are required to confirm this." (PMID 35902379, 2022). "Patterson and co-workers have also shown that CYP1A1, as one of several CYPs, contributes in the conversion of the hypoxia-activated prodrug AQ4N to the topoisomerase II inhibitor AQ4, which has shown promise in a phase I trial that included six breast cancer patients." (PMID 33809117, 2021). "In addition, the breast cancer cells in the THC + CYP1A1 group undergo almost no apoptosis." (PMID 36707875, 2023). "Interestingly, recent studies have shown that CYP1A1 promotes breast cancer progression even in the absence of xenobiotics and suggests the possibility that this gene may be involved in other carcinogenic mechanisms." (PMID 27203547, 2016). "Interestingly, a recent study has also revealed that the attenuation of CYP1A1 could prevent breast cancer progression even in the absence of xenobiotics." (PMID 27203547, 2016). "Although prior studies have not examined whether associations of CYP1A1 rs2606345 with mammographic density vary by BMI, a prior study reported that the association of an ESR1 SNP with increased breast cancer risk was apparent only among women with BMI greater than 25 kg/m2." (PMID 19630952, 2009). "SFN reduced CYP1A1 protein level equally in nontumorigenic MCF10A breast cells, ER(+) MCF7, and ER(−) MDA-MB-231 breast cancer cells, but the increased level of CYP1A2 and the decreased level of CYP1B1 expression were found only in MCF10A cells." (PMID 40807256, 2025). "The constitutive mRNA expression and cellular content of CYP1A1 and CYP1B1, AhR-regulated genes, were markedly higher in CSCs more than differentiating non-CSCs of five different human breast cancer cells." (PMID 28103884, 2017). "In human breast cancer cell lines, higher CYP1B1 expression over CYP1A1 has been related to higher AhR expression and ERα-negative status." (PMID 26715507, 2015). "SFN reduced the CYP1A1 protein level equally in nontumorigenic MCF10A breast cells, ER-positive MCF7, and ER-negative MDA-MB-231 breast cancer cells, but the increased level of CYP1A2 and the decreased level of CYP1B1 expression were found only in MCF10A cells." (PMID 39339278, 2024). "Moreover, rodent and human mammary tumors overexpress constitutively active AHR, which is characterized by elevated CYP1B1 but not CYP1A1 mRNA." (PMID 31652854, 2019). "We showed that AF could activate a DRE-driven luciferase reporter and induce expression of CYP1A1 and CYP1B1 in AF-sensitive, ERα-negative MDA-MB-468 human breast cancer cells." (PMID 24885022, 2014). "In particular, it was reported that luteolin could be metabolized into 6 hydroxyluteolin by recombinant CYP1B1, but not by CYP1A1 and CYP1A2, and that hydroxylation of luteolin at the 6 position of the A ring is crucial for the antiproliferative activity in breast cancer cells." (PMID 34594472, 2021).
lung carcinoma (108 papers, 2000 to 2025). "Elevated CYP1A1 expression has been associated with cancer progression, and its genetic polymorphisms are linked to increased risks of breast and lung cancers 31-33." (PMID 41209569, 2025). "Previous studies have supported that CYP1A1 polymorphisms played a role in the pathogenesis of lung cancer." (PMID 40175891, 2025). "Genetic polymorphisms of cytochrome p450 1A1 (CYP1A1) are thought to modulate the risk in lung cancer." (PMID 40175891, 2025). "Recent research has covered the genetic polymorphisms of CYP1A1 carried weight with the risk of developing cancers containing lung cancer, upper digestive tract cancer, and thyroid carcinoma." (PMID 36685893, 2022). "The variant rs1048943/CYP1A1 was associated with lung cancer risk in East Asians51, which shows the colinearity of this study's findings to the present study as discussed here." (PMID 34272429, 2021). "Our replication meta-analysis across the world population justifies the role of the variant rs1048943 (CYP1A1) in conferring lung cancer risk among smokers with a higher power." (PMID 34272429, 2021). "CYP1A1 6235T > C variant raises the risk for solid tumors, for example lung cancer, cervical cancer, prostate cancer and laryngeal cancer." (PMID 34830558, 2021). "The variant rs1048943A > G of CYP1A1 locus is a non-synonymous polymorphic variant, which imparts an individual effect on lung cancer risk in various populations." (PMID 34272429, 2021). "CYP1A1 gene variants have been linked to cancer susceptibility, for example in acute myeloid leukemia, prostate cancer, larynx cancer, lung cancer and MM." (PMID 34830558, 2021). "Particular CYP1A1 alleles have been associated with lung cancer, whose incidence is highly correlated to environmental exposure of agents, such as polyaromatic hydrocarbons (PAHs)." (PMID 32197424, 2020). "Previous study showed that the polymorphism of CYP1A1 was associated with the treatment outcome of EGFR-TKI in advanced lung cancer patients." (PMID 32457635, 2020). "We observed that the CYP1A1 polymorphism, CYP1A1 I461V that was linked to a higher incidence of human lung cancer, actually conferred lower levels of genotoxicity in yeast exposed to carcinogens, compared to CYP1A1." (PMID 32197424, 2020). "Cytochrome P450 Family 1 Subfamily A Member 1 (CYP1A1) was also found high polymorphic and associated with elevated risk of lung cancer." (PMID 31641374, 2019). "The strongest smoking-related expression signal was in the CYP1A1 gene—a lung cancer susceptibility gene, which was also one of the differentially methylated signals." (PMID 30342560, 2018). "Asian reports rarely observed presence of CYP1A1*4 variant, meanwhile, it was more common among whites and it was reported, by itself, as a lung cancer risk factor in Caucasians." (PMID 28074113, 2017). "In this work, we aimed to identify CYP1A1 gene polymorphisms associated with lung cancer in Egyptian population and to examine the interaction effect with Tobacco smoking in modulating disease risk." (PMID 28074113, 2017). "In an Australian study to identify lung cancer-risk modifying CYP1A1 haplotypes, *2A and *2C variants were significantly over-represented in NSCLC cases compared to controls, whereas *4 variant was under-represented." (PMID 28074113, 2017). "There was statistical significant difference in the distribution of CYP1A1 variants in relation to smoking habit among lung cancer patients and control subjects." (PMID 28074113, 2017). "The aim of this work is to identify CYP1A1 gene polymorphisms associated with lung cancer in Egyptian population and to examine the interaction effect with Tobacco smoking in modulating disease risk." (PMID 28074113, 2017). "In Egyptian population, CYP1A1 I462V, T461N and I286T variants were identified among lung cancer patients and combined T461N/ I462V was a risk variant for NSCLC in non smokers." (PMID 28074113, 2017).